HIF1A (hypoxia inducible factor 1 subunit alpha)
Diseases named in the same sentence as HIF1A in open-access papers (continued):
Sharing a sentence is not in itself a finding about the gene and the disease.
tumor (continued). "Hypoxia can induce glycolysis in macrophages, for example tumor‐associated macrophages (TAMs) present in the hypoxic regions of tumors express HIF‐1α inducing a switch to glycolytic fermentation." (PMID 33363732, 2020). "Tumor-derived extracellular vesicles (TEVs) include RNA and a variety of cytokines such as TGF-β, activated Src, Wnt3, HIF1α, in which the process also associates with tumor progression." (PMID 33224886, 2020). "Pathological hypoxia is present in the majority of human solid cancers and is associated with increased tumor aggressiveness and therapeutic resistance, in part through activation of HIF-1α." (PMID 32695673, 2020). "The pre-exposure of NK cells to hypoxia, through HIF1-α stabilization, causes cells to adapt toward a cytolytic phenotype and acquire tumor immune-surveillance activity." (PMID 32764403, 2020). "In the hypoxic microenvironment, macrophages accumulation and polarization contribute to tumor angiogenesis and creation of an inflammatory environment which is associated with hypoxia-inducible factor (HIF)-1α (HIF-1α)." (PMID 33245358, 2020). "To understand the changes in tumor infiltration of innate immune cells caused by reduced HIF-1α activity, we analyzed the levels of cytokines in tumor homogenates." (PMID 33142239, 2020). "Potentially this reduced HIF-1α stabilization phenotype can lead to a reduced tumor take in vivo however the precise underlying mechanisms should be further elucidated." (PMID 32509579, 2020). "It is possible that the extreme conditions inside the tumor, such as hypoxia, can cause aberrant expression of certain genes, such as HIF1α, leading to metabolic reprogramming." (PMID 33298893, 2020). "For instance, tumor-associated macrophages (TAMs) were shown secreting EVs packaged with a long noncoding RNA (HISLA) that stabilized HIF-1α in breast cancer cells." (PMID 32992699, 2020). "Several processes appear to underlie the influence of βAR on tumor progression, including increased HIF-1α signaling and angiogenesis." (PMID 32413989, 2020). "On the other hand, in a mouse model of glioblastoma, mutant mice bearing HIF1α‐deficient Tregs showed better survival than controls due to impaired Treg migration to tumor sites." (PMID 33067808, 2020). "HIF-1α was found to be the main cause of the tumor microenvironment effect on the differentiation and function of MDSCs." (PMID 33027968, 2020). "Accordingly, HIF-1α inhibitor increased human NK cell activity, and low HIF-1α expression was associated with high expression of IFN-ɣ in human tumor-infiltrating NK cells." (PMID 33260925, 2020). "LncRNA HISLA, packaged in extracellular vesicles from tumor-associated macrophages, stabilizes HIF-1α and inhibits degradation by binding to PHD2 in glycolytic tumor cells." (PMID 33050646, 2020). "As a result of loss of function of various tumor suppressors, the levels of HIF1A increase, indicating that higher HIF1 activity is a common pathway in the pathogenesis of various human cancers." (PMID 33167967, 2020). "In human HNSCC, the acidic TME has been reported to promote HIF-1α activation and tumor-associated macrophage (TAM) expression of M2-specific markers CSF1R and CD163, as well as driving concomitant production of arginase and VEGF." (PMID 35047983, 2020). "Hypoxia not only has been shown to activate several pathways via stabilization of the transcription factors associated with tumor progression HIF-1α and HIF-2α but also has been identified as a critical parameter of the tumor microenvironment." (PMID 32993034, 2020). "Tumours with HIF1A loss were statistically more likely to have higher grade and stage, and display lymph node positivity and metastases, consistent with this subgroup representing a more aggressive form of ccRCC." (PMID 32807776, 2020). "Reportedly, HIF-1A–induced GLUT1 overexpression causes the accumulation of lactic acids in the tumour microenvironment, resulting in the suppression of CD8+TILs." (PMID 32238919, 2020).
tumor (continued). "The HIF proteins, especially HIF‐2α and HIF‐1A, are associated with the metastasis and development of tumor, and advance the epithelial‐mesenchymal transition." (PMID 32061057, 2020). "In contrast, it have been reported that HIF‐1α expression in ccRCC was associated with the good prognosis, and HIF‐1α acts as a tumour suppressor in ccRCC." (PMID 32537867, 2020). "Recent studies have revealed that the overexpression of HIF-1α in HCC is closely associated with tumor angiogenesis, metastasis, treatment resistance, and poor prognosis." (PMID 32516967, 2020). "Hypoxia or von Hippel-Lindau (VHL) tumor suppressor loss leads to the stabilization of hypoxia-inducible factors alpha (HIF-1α and HIF-2α) and the activation of their signaling to mediate adaptive responses." (PMID 32733884, 2020). "The HIF-1α expression was significantly associated with smoking, tumor category, differentiation degree, TNM Stage, Lymph metastasis (all P<0.05)." (PMID 32054470, 2020). "They found that stabilization of HIF-1α and increased phosphorylation of the signal transducer and activator of transcription 3 (pSTAT3), in tumor cells, were associated with evasion of immune surveillance." (PMID 33117715, 2020). "HIF1α expression is associated with the low tumor grade and favorable prognosis while expression of HIF2α correlated with high tumor grade and unfavorable prognosis." (PMID 32722460, 2020). "There is also a recent meta-analysis study demonstrated that HIF-1α overexpression is associated with tumor size, tumor stage, lymph node metastasis, and overall survival of patients with OSCC." (PMID 32597160, 2020). "HIF-1α expression from tumor infiltrating lymphocytes, tumor associated macrophages has been studied for its potential role in cancer progression and metastasis (Wigerup, Påhlman & Bexell, 2016)." (PMID 30746305, 2019). "In CCA, high expression of HIF-1α promotes tumor progression and metastasis and is associated with poor patient survival." (PMID 31921870, 2019). "A tumor-derived lactic acid-induced expression of VEGF by an HIF1α-driven mechanism has recently been shown in tumor-associated macrophages." (PMID 31540455, 2019). "We found that HIF1A transcription response in hypoxia is driven by epigenetic control of low oxygen levels and can upgrade high-risk tumor features." (PMID 30808328, 2019). "Initially, it was identified due to its sensitivity to low O2 levels, but it is now clear that HIF-1α can also be regulated by other factors, such as the activation or loss of tumor oncogenes or suppressors." (PMID 31208103, 2019). "For example, lactic acid produced by glycolytic tumor cells, induces a HIF-1α-dependent polarization of tumor-associated macrophages." (PMID 31032261, 2019). "In mice with a Treg-restricted HIF1α deficiency, the reduced Treg recruitment to the site of a growing glioma leads to significantly delayed tumor growth and longer survival." (PMID 31507585, 2019). "Other histone-modifying enzymes are also directly linked to HIF-1α protein stability and involved in the promotion of tumor growth." (PMID 30939818, 2019). "Hypoxia is a key concern during the treatment of tumors, and hypoxia-inducible factor 1 alpha (HIF-1α) has been associated with increased tumor resistance to therapeutic modalities." (PMID 31569523, 2019). "In conclusion, the results of the present study suggest that in patients with OC, the expression level of hypoxia-inducible factor 1 alpha (HIF-1α) is inversely associated with tumor pharmacokinetic DCE-MRI perfusion parameters Ktrans and Kep." (PMID 31437208, 2019). "We identified that BAP1 loss is strongly associated with the expression of HIF1a, even after adjustment for tumour size or chromosome 3 status." (PMID 31323773, 2019). "Mutations of the von Hippel-Lindau (VHL) tumor-suppressor gene and the resultant overexpression of hypoxia-inducible factor (HIF)-1α protein are considered hallmarks of ccRCC." (PMID 30909494, 2019).
tumor (continued). "For example, under hypoxia, translation of pro‐growth mRNAs is largely inhibited, while that of mRNAs encoding HIF1α and other stress proteins is enhanced to promote survival of hypoxic tumor cells." (PMID 31668005, 2019). "Recently, it has been reported that SAA1 the expression levels in GBM patients are upregulated on both mRNA and protein in human GBMs, and SAA1 involves in angiogenesis via HIF-1α and tumor associated macrophages." (PMID 30867991, 2019). "The tumor has been associated with hypoxia, which stabilizes HIF-1α, which is a transcriptional activator of various genes, to upregulate VEGF levels and promote vascular growth and tumor progression." (PMID 30935077, 2019). "The hypoxic environment in tumors is an important factor that causes tumor metastasis by activating hypoxia-inducible factor-1α (HIF-1α)." (PMID 31041568, 2019). "HIF1α has been implicated in the differentiation of MDSCs to suppressive tumor-associated macrophages, while Gαi signaling is required for the activation of STAT380,81, an important transcription factor in PMN-MDSC development and function." (PMID 30837603, 2019). "HIF-1α is a transcription factor, and its high expression is associated with poor outcomes in most malignancies and tumor resistance to therapy." (PMID 31533363, 2019). "Those that do survive will be in a high expression of HIF-1α, causing tumor recurrence and metastasis after initial treatment." (PMID 30911540, 2019). "Among the signaling pathways adapted to this harsh microenvironment, HIF-1α activation has been extensively reported and implicated in tumor invasiveness and metastasis." (PMID 30630537, 2019). "In the TCGA data, it was confirmed that BAP1 loss relates to increased HIF1a expression within M3 tumours." (PMID 31323773, 2019). "Hypoxia inducible factor-1α (HIF-1α) is a key regulator of cellular response to hypoxia and plays an important role in tumor growth, and HIF-1α gene single-nucleotide polymorphisms (SNPs) adversely affect the outcome in some cancers." (PMID 30678691, 2019). "The IDH1/2 mutations can upregulate VEGF to promote tumor microvessel formation by inhibiting the breakdown of HIF-1α." (PMID 31263678, 2019). "Cox univariate and multivariate analyses showed that HIF-1α and c-myc protein expression, histological grade, lymph node status, and tumor TNM stage were the independent risk factors for postoperative survival in TNBC patients." (PMID 31577739, 2019). "Increased expression of HIF-1α, a marker of tumor hypoxia, is well associated with carcinogenesis and tumor progression in various kinds of cancer." (PMID 30782196, 2019). "Under hypoxic conditions, overexpression of HIF-1α changes the proteome and genome of tumor cells, causing the tumor microenvironment to contribute to treatment resistance and metastasis." (PMID 31695774, 2019). "Conversely, UCP knockdown increases pVHL levels, causing a decrease in HIF-1α levels and inhibiting tumor growth." (PMID 31221957, 2019). "A study showed that transfection of glioma cells with IDH1 mutation leads to the upregulation of HIF1-α and to increased tumor cell proliferation." (PMID 30708988, 2019). "Both patients were found to be negative for mutations in erythropoietin, erythropoietin receptor, HIF-1α, janus kinase 2, prolyl hydroxylase, succinate dehydrogenase B/C/D, and von Hippel-Lindau genes in circulating leukocytes and resected tumor tissues." (PMID 31185588, 2019). "It has been shown that the up-regulation of HIF-1α activity promotes tumor-associated angiogenesis, and hence the survival and proliferation of tumor cells in solid tumors." (PMID 30367150, 2019). "Within tumor cells, HIF-1α has been associated with a shift toward anaerobic metabolism and the expression of numerous genes involved in angiogenesis, apoptosis, pH regulation, and cellular differentiation." (PMID 31569523, 2019).
tumor (continued). "Zhou and co-workers showed an association of overexpression of HIF-1α with tumor size, tumor stage, lymph node metastasis, and overall survival." (PMID 30654595, 2019). "Overexpression of HIF-1α was found to be associated with tumor size and depth of invasion, while expression of CD73 is markedly increased in metastatic cancers." (PMID 31396523, 2019). "More recently, however, the loss of HIF-1α in knockout (KO) mice inhibited tumor growth even though tumor killing was impaired." (PMID 31396523, 2019). "Tumor HIF-1α protein levels were associated with 10-year disease-specific survival (P = 0.035) but not with disease-free survival (P = 0.451)." (PMID 30943919, 2019). "BCL2, c-FOS and HIF1a are transcription factors, whose dysregulation were broadly reported to be associated with tumor inflammation, angiogenesis, and suppression of apoptosis among others." (PMID 31754348, 2019). "With high expression of a hypoxia, serial autophagy markers, such as BNIP3, LC3B and ATG5, were found modulated by HIF1α, and these were often associated with aggressive tumor progression phenotype in vivo." (PMID 31700698, 2019). "Other small molecules like YC-1, thioredoxin inhibitors, 17-AAG, and 2ME2 were associated with the capacity of reducing the HIF-1α levels together with limitation of tumor growth and angiogenesis in vivo." (PMID 31817513, 2019). "A higher level of oxygen has been associated with downregulation of HIF-1α protein in tumors which is critical for tumor treatment." (PMID 30609703, 2019). "HIF1A is a key factor in the hypoxic microenvironment and is closely related to the expression of various tumor-associated factors." (PMID 31930127, 2019). "We found that acute hypoxic response results in increased lung metastatic tumours, caused by HIF-1α-dependent endothelial cell death and increased microvascular permeability, in turn facilitating extravasation." (PMID 31308473, 2019). "It is well-documented that the mutation of the VHL tumor suppressor gene promotes the constitutive activation of HIF-1α and HIF-2α subunits in RCC." (PMID 30909494, 2019). "Hypoxia-inducible factor 1 alpha (HIF1α) is one of the most potent factors that are widely linked to the behavior changes of hypoxic tumor cells." (PMID 31752873, 2019). "The increased HIF-1α levels have been correlated with the promoted tumor angiogenesis and aggressive tumor growth, causing poor prognosis and treatment failure in a number of cancers." (PMID 29498688, 2018). "Here we have found that K-ras mutant lung tumorigenesis and its promotion by COPD-like airway inflammation is associated with significant tumor angiogenesis and activation of HIF-1α." (PMID 30250643, 2018). "Hypoxia inducible factor-1α (HIF-1α) is known to regulate the expression of many chemokines, including interleukin-8 (IL-8), which is associated with tumor metastasis." (PMID 30258464, 2018). "First, hypoxia-inducible factor 1-α (HIF1-α)-mediated tumor-associated hypoxia increases PD-L1 expression on the surface of tumor-infiltrating MDSCs, thus resulting in the inhibition of T cell activity by binding to PD-1 expressed on T cells." (PMID 29735917, 2018). "HIF-1α activation can suppress immunity or promote tumor evasion, however the underlying molecular mechanisms remain to be further identified." (PMID 29458370, 2018). "Inactivation of HIF-1α in Tie2 positive ECs lead to decreased tumor growth in a subcutaneous LLC model, caused by reduced density of tumor vessels." (PMID 29896451, 2018). "Hypoxia elicited by hypoxia-inducible factor (HIF)-1α dramatically alters the function of MDSCs in the tumor microenvironment and redirects their differentiation toward tumor-associated macrophages (TAMs)." (PMID 30237829, 2018). "We found that a low level of HIF-1α mRNA is significantly associated with a 2.8-fold increased risk of tumor-related death in STS patients (p = 0.001)." (PMID 30513863, 2018).
tumor (continued). "Although HIF-1α is known for its hypoxia-responsive feature, it is regulated by many other factors under normoxia condition such as loss of tumor suppressors, reactive oxygen species (ROS) or oncogene activation." (PMID 29662084, 2018). "In a xenograft model for tumorigenesis, ablation of the hypoxic inducibility of LIMD1 expression and subsequent loss of hypoxic HIF‐1α protein regulation caused increased tumour vasculature and growth." (PMID 29930174, 2018). "Among them, ATM (associated with DNA repair) and HIF‐1α (associated with hypoxia in tumor microenvironment) are possibly correlated with radiosensitivity in A549 cells and CD133+ stem‐like cells." (PMID 29860718, 2018). "Tumor hypoxia is known to recapitulate the HMM microenvironment of the body cavity with HIF-1α expression, and EMT has been potentially implicated in mesothelial carcinogenesis." (PMID 30111297, 2018). "HIF-1α is a key transcription factor induced by hypoxia and it activates the transcription of genes implicated in tumor angiogenesis, cell survival, and resistance to chemotherapeutic drugs." (PMID 29568752, 2018). "Airway epithelial specific HIF-1α deficient mice demonstrated significant reductions in lung surface tumor numbers, tumor angiogenesis, and tumor cell proliferation in the absence or presence of COPD-like airway inflammation." (PMID 30250643, 2018). "Accordingly, constitutional deficiency of COMMD1 leads to broad activation of HIF-1α and embryonic lethality, while its deficiency in cancer cells promotes HIF-1α-dependent gene expression and tumor cell invasion." (PMID 30487795, 2018). "The loss of the VHL tumor suppressor in renal carcinomas is well known to lead to increased stabilization HIF1α and a glycolytic metabolism." (PMID 29361779, 2018). "Xenograft studies have revealed that loss of expression of HIF-1α inhibited tumor growth and, in contrast, deficiency of HIF-2α stimulated tumoral cell proliferation." (PMID 30619282, 2018). "Branco-Price and colleagues described that deficiency of HIF-1α in the endothelium diminishes NO synthesis, resulting in retarded tumor cell migration and consequent tumor cell metastasis." (PMID 29434587, 2018). "First, they found that tumor-specific gained enhancers were associated with important oncogenic signaling and the hallmarks of ccRCC, including HIF1α signaling and pro-angiogenesis pathways." (PMID 29562667, 2018). "In subcutaneous xenografts derived from HIF-1α deficient embryonic stem cells, HIF-1α deficiency resulted in accelerated tumor growth, decreased perfusion, and increases in tumor hypoxia as observed by pimonidazole staining." (PMID 30420794, 2018). "The results of the current study are in line with that previous data in that low mRNA levels of EGFR or HIF-1α mRNA are associated with poor tumor-specific survival." (PMID 30513863, 2018). "A higher affinity for lactate (vs. pyruvate) makes MCT4 the bona fide transporter of lactate outside glycolytic tumor and tumor-associated cells, a function further supported by hypoxia-inducible factor-1α (HIF-1α)-mediated MCT4 gene upregulation." (PMID 29572438, 2018). "HIF-1α signaling is associated with tumor metastasis, tumor angiogenesis, and a poor patient prognosis, as well as resistance to tumor therapy." (PMID 29416815, 2018). "In tumor metabolism, oxidative and reductive glutamine metabolism was found to be significantly impaired in HIF-1α/Anxa1-deficient cells, and associated with lower proliferation." (PMID 30213070, 2018). "The continuous and dysplastic growth of tumor determines the formation of hypoxic microenvironment that induces the stabilization of HIF1-α and its association with HIF1-β)." (PMID 29351242, 2018).